CPLANE2 (ciliogenesis and planar polarity effector complex subunit 2)
Description:
Required for efficient primary cilia initiation, regulating a late step in cilia initiation. Plays a role in the final maturation of the mother centriole and ciliary vesicle that allows extension of the ciliary axoneme.
Synonyms: C1orf89; RSG1; MGC10731
Tractability: No criterion of Open Targets' tractability assessment is met for any kind of drug.
Gene: Protein-coding gene on chromosome 1 (16,231,692 to 16,237,183, reverse strand). Ensembl gene ENSG00000132881.
Subcellular location: Cytoplasm, cytoskeleton, cilium basal body; Cytoplasm, cytoskeleton, microtubule organizing center, centrosome, centriole
Subcellular location (Human Protein Atlas): Nucleoplasm; Cytosol; Nuclear bodies
Gene Ontology:
Molecular function: protein binding; GTP binding; GTPase activity
Biological process: axoneme assembly; cilium assembly; intracellular protein localization; regulation of exocytosis; regulation of vesicle fusion
Cellular component: centriole; ciliary basal body; ciliary transition zone; ciliary base; microtubule organizing center
Genetic constraint (gnomAD): Loss-of-function variants: 25 observed, 21.07 expected, observed/expected ratio (o/e) 1.19, 90% interval 0.86 to 1.65. The upper end of that interval is the gene's LOEUF score, 1.65, which puts it in group 6 of 6, group 1 being the genes least tolerant of losing a copy. Missense variants: 330 observed, 353.68 expected, observed/expected ratio (o/e) 0.93, 90% interval 0.85 to 1.02. Synonymous variants: 132 observed, 142.72 expected, observed/expected ratio (o/e) 0.92, 90% interval 0.8 to 1.07.
Homologues: Orthologues: chimpanzee CPLANE2 (99% identical), macaque CPLANE2 (97% identical), pig CPLANE2 (93% identical), dog CPLANE2 (92% identical), guinea pig CPLANE2 (90% identical), mouse Cplane2 (89% identical), rat LOC120103024 (89% identical), rabbit CPLANE2 (88% identical), tropical clawed frog cplane2 (58% identical), zebrafish cplane2 (52% identical).
Diseases named in the same sentence as CPLANE2 in open-access papers:
CPLANE2 is named in the same sentence as 6 diseases in open-access papers, as found by Europe PMC text mining. Sharing a sentence is not in itself a finding about the gene and the disease.
CPLANE2 shares sentences with these, for which no sentence is quoted: cancer (1 paper); ciliopathies (1); gout (1); heart failure (1); Hypertension (1); tumor (1).